PDGFRA (platelet derived growth factor receptor alpha)
Diseases named in the same sentence as PDGFRA in open-access papers (continued):
Sharing a sentence is not in itself a finding about the gene and the disease.
tumor (continued). "In previous years, we tried to expand the platform by collecting several PDGFRA-mutated tumor samples and tumor samples of the historically called ‘wild-type’ genotype, i.e. GIST with mutations other than KIT or PDGFRA." (PMID 39853155, 2025). "Mechanistically, Twist1 drives invasive pseudopod formation through coordinated induction of platelet-derived growth factor receptor α (PDGFRα) expression and Src kinase activation, thereby potentiating tumor cell invasion." (PMID 40530008, 2025). "Intragenic mutations in EGFR and PDGFRA produce functionally active variants that not only enhance cell division, but also modify the TME, promoting tumor invasion and facilitating angiogenesis." (PMID 40868137, 2025). "Immunoreactivity for PDGFRA was observed in a minor fraction of the pre-treatment tumor suggesting that PDGFRA-altered clones were already present (PDGFRA)." (PMID 40819143, 2025). "GBM is marked by genetic alterations, including EGFR amplification, PDGFRA mutations and IDH1/2 mutations, which drive tumor development and contribute to treatment resistance." (PMID 39781344, 2025). "Abnormal activation of the PDGFRα pathway induces tumour neovascularization, which directly or indirectly promotes tumour cell proliferation and metastasis." (PMID 39827226, 2025). "Specifically, the open chromatin loop conformation favors the use of GSX2 regulatory components for the co-option of PDGFRA-dependent tumor growth." (PMID 40813437, 2025). "To determine INSM1 expression dynamics during the evolution of PRO human GBM, we performed scRNA-seq analysis of 11,384 cells from a patient tumor with PDGFRA amplification." (PMID 41354838, 2025). "Tumor-derived VEGFA and TGFβ2 signals were received by NRP2 and TGFβR2/3 receptors present on MES and RG-PC cells, respectively, with PDGFA_PDGFRA signaling from tumor cells directing final PC specification." (PMID 40562749, 2025). "Given PDGFRA’s established role as a promoter of tumor angiogenesis, these findings further corroborate the evidence that PRG4 plays an inhibitory role in neovascularization." (PMID 41327374, 2025). "In preclinical studies, the PDGFRA inhibitor avapritinib demonstrated significant decrease in tumor growth and improved survival in mouse models of pediatric PDGFRA mutated H3K27M DMG." (PMID 40094009, 2025). "Similar results were obtained by Sulzbacher et al15 PDGFRα overexpression (staining of >38.8% of 500 cells) correlated with the tumor grade (G3-4)." (PMID 40434293, 2025). "THY1 enhances CAF activity, leading to an immunosuppressive environment, while PDGFRA fosters fibrosis, further hindering immune cell access to the tumor." (PMID 40817072, 2025). "It specifically and durably inhibits the KIT proto-oncogene receptor tyrosine kinase (KIT) and the platelet-derived growth factor receptor A (PDGFRA), thus suppressing tumor cell growth." (PMID 40231257, 2025). "In the relma-cel study, the expression levels of tumor-associated fibroblast markers (AP, TNC, CSPG4, PDGFRA, S100A4, ASPN, STC1, and ITGAM) were higher in the patients with PR than with CR." (PMID 39858099, 2025). "Expression levels were quantified using the semi-quantitative H-score (HS) method, and correlations between PDGFRα/β expression and tumor characteristics were evaluated." (PMID 40434293, 2025). "In conclusion, our integrative genomic and transcriptomic analysis highlights PDGFRA as a potential therapeutic target, owing to its high mutation frequency, elevated expression in specific OPC‐like subpopulations, and tumor‐driving potential." (PMID 41036308, 2025). "GBM cells are distinguished by the presence of PDGFRs, specifically PDGFRα and PDGFRβ, which are overexpressed and persistently active in this type of tumor." (PMID 40332008, 2025).
tumor (continued). "In C3A and SNU-398, which exhibit high expression of PDGFRA, the combination of avapritinib and lenvatinib demonstrated a robust synergistic inhibitory effect on tumor cell growth." (PMID 40336047, 2025). "PDGF-CC, PDGF-DD, and PDGFRα were predominantly expressed in tumor cells, whereas PDGFRβ was localized primarily to the vascular stroma." (PMID 40508013, 2025). "Early and accurate identification of specific tumor mutations, such as KIT, PDGFRA, or SDH deficiencies, allows for tailored therapeutic strategies that can significantly improve prognosis and survival rates." (PMID 39927693, 2025). "The results from TCGA_LIHC and GEO databases (GSE76427) revealed that compared with RGS5+ CAFs, substantial infiltration of TAMs and PDGFRα+ CAFs was observed in tumours." (PMID 39827226, 2025). "Altogether, our data indicate that one of the molecular mechanisms by which Endocan affects GBM is binding to PDGFRA and subsequent activation of the downstream signaling pathways in tumor cells adjacent to VE cells in the microvasculature proliferation area." (PMID 39773984, 2025). "In vivo, inhibition using imatinib or PDGFRα-neutralizing antibodies significantly reduced tumor growth, particularly in larger lesions." (PMID 40508013, 2025). "This study identifies COL1A1, ITGB1, THY1, and PDGFRA as crucial regulators of UCEC progression, with altered expression linked to tumor behavior and patient survival." (PMID 40817072, 2025). "The amplification of chromosomal regions containing the genes EGFR, MET, KIT, and PDGFRA is associated with the receptor tyrosine kinase (RTK) and growth-factor receptors, often driving proliferative and angiogenic signalling in tumours." (PMID 41573648, 2025). "PDGFRA’s role in regulating cell proliferation and survival can impact the tumor microenvironment and immune cell infiltration, contributing to the observed gender differences." (PMID 40458476, 2025). "Theses 13 genes (e.g., COL1A1, POSTN, ASPN, PDGFRA, MUC4, SPARC), implicated notably in EMT and cancer progression, were found to be highly expressed in depth of tumor ID15 and ID08, near the invasive margin." (PMID 40076457, 2025). "In particular, PDGFC induces increased PDGFRA expression in both tumor cells and fibroblasts, which can lead to reciprocally positive feedback to accelerate malignant tumor progression." (PMID 40501228, 2025). "Correlation analyses indicate that GREM1 is significantly positively correlated with genes associated with tumor invasion and metastasis, including TWIST1 and PDGFRA." (PMID 40066442, 2025). "In conclusion, the expression of the tyrosine kinase receptors PDGFRα and, to a somewhat lesser extent, PDGFRβ, was detected on the surface and in the cytoplasm of primary tumor cells of patients with RCC stage pT1a-T4N0/+M0/+." (PMID 40434293, 2025). "Approximately 85% of GISTs harbor mutually exclusive activating mutations in KIT (exons 9, 11, 13, 17) or PDGFRA (exons 12, 18), driving constitutive receptor tyrosine kinase (RTK) activation and tumor progression." (PMID 40900786, 2025). "Avapritinib treatment was initiated based on the discovery of PDGFRA alterations in the recurrent tumor." (PMID 40819143, 2025). "Lower PDGFRA level impair signaling pathways regulating tumor growth and progression, leading to reduced angiogenesis, invasion, and metastasis." (PMID 40817072, 2025). "Inflammation-associated CAFs (Pdgfrα+ CAFs) were subsequently identified, which demonstrated a significant correlation with the survival duration of HCC patients and a dual role in the tumour microenvironment (TME)." (PMID 39827226, 2025). "In OC, emerging evidence has proposed a role for PDGFRα in the maintenance and acquisition of stem-like phenotypes, which can promote tumour aggressiveness and treatment resistance." (PMID 41463341, 2025). "Early tumor evolution is marked by CDKN2A/B loss and EGFR, platelet-derived growth factor receptor A (PDGFRA), and CDK4 gains." (PMID 40565099, 2025).
tumor (continued). "Platelet-derived growth factor receptor alpha expression correlated with tumor grade (r = 0.471; P < .0001) and the pN+ category (r = 0.280; P = .024)." (PMID 40434293, 2025). "For example, in addition to targeting KIT and PDGFRA, imatinib has also been shown to act on host dendritic cells to enhance anti-tumour effects in vivo by promoting NK cell activation." (PMID 39070147, 2024). "PDGFRA is positively correlated with multiple immune checkpoints and modulation genes, suggesting its significant role in the tumour immune environment." (PMID 39063239, 2024). "For example, the PDGFRA gene is related to tumour angiogenesis, which is a key factor in tumour growth and metastasis." (PMID 39120548, 2024). "First, tumour adaptation to KIT/PDGFRA inhibition likely leads to apoptosis evasion and GISTs survival through two intertwined events." (PMID 39070147, 2024). "We also demonstrated that high expression of NUMBL and PHF21A, but low expression of PDGFRA in tumor tissues compared with normal tissues." (PMID 38167072, 2024). "High expression of PDGFRβ and PDGFRα in the tumor stroma was observed in 83% (205/248) and 74% (183/248), respectively." (PMID 38791897, 2024). "In gastric GISTs, aberrant activation of KIT and PDGFRA promotes tumor growth and progression by stimulating cell cycle progression, enhancing angiogenesis, and facilitating evasion of immune surveillance mechanisms." (PMID 39064037, 2024). "We further investigated the consequence of PDGFRA regulation by autophagy using a mouse model for gliomagenesis where we observed a disruption in PDGFA-driven tumor formation when autophagy is inhibited." (PMID 38634484, 2024). "Next, we performed multiplex immunohistochemistry analysis on ID8TB−/− tumors from WT and Ddr2−/− mice for expression of Arg1 and various tumor stromal cell type markers (CAF – PDGFRα; macrophage – F4/80)." (PMID 37996700, 2024). "Our stromal score analysis showed a favourable link between the expressions of genes such as LRP1, FGF7, FOS, PI3, PAEP, and PDGFRA and tumour purity in our investigation of the effect of IRGs on OC’s TME." (PMID 39063239, 2024). "In this case, since the tumor appeared to be a rare tumor, we used the Illumina TruSight assay up front and discovered the PDGFRA::USP8 gene fusion." (PMID 38401149, 2024). "KIT/PDGFRA WT-GISTs are a genomically heterogeneous group of neoplasms, representing 10–15% of all GISTs." (PMID 39199677, 2024). "There is growing evidence linking altered PDGFRα-mediated signaling with increased tumor progression and metastasis." (PMID 38473265, 2024). "CAFs can promote tumor cell mitotic proliferation via PDGFC/PDGFRA/SLUG, achieving metastasis and immune escape by regulating E2F, signal transducer and activator of transcription 5 (STAT5), etc.." (PMID 39015573, 2024). "The most frequent alteration, present in 16 DMGs, was an amplification of the platelet-derived growth factor alpha (PDGFRA), which also plays a role in tumour cell proliferation and migration." (PMID 39256213, 2024). "NUMBL and PHF21A were upregulated but PDGFRA was downregulated in tumor samples compared with normal samples in the Human Protein Atlas (HPA) database." (PMID 38167072, 2024).
tumor (continued). "Consistent with the findings above, MEDI-575, a human-neutralizing monoclonal antibody explicitly targeting PDGFRα, has been shown to reduce tumor growth in NSCLC cancer models through modulation of stromal fibroblasts." (PMID 39403603, 2024). "Regorafenib is an oral multi-targeted TKI, whose targets are involved in the regulation of tumor angiogenesis (VEGFR1–3 and TEK), oncogenesis (KIT, RET, RAF1, BRAF, and and BRAFV600E), and maintenance of the tumor microenvironment (PDGFRA, PDGFRB and FGFR)." (PMID 39165680, 2024). "Jilg and colleagues conducted a prospective clinical trial to assess the presence of tumor-specific c-KIT and PDGFRA mutations in GIST patient plasma." (PMID 37046997, 2023). "Critically, the most significant difference between tdTomato+PDGFRα+ cells from Snail1ME-WT and Snail1ME-KO tumours corresponds to the signature of the S1 (“immune”) population, associated to higher expression of immunomodulatory factors." (PMID 37516803, 2023). "PDGFRA promotes tumor development by activating downstream signaling kinases, such as extracellular signal-regulated kinase (ERK), AKT and S6 K." (PMID 36829235, 2023). "Recent evidence supports its role in tumor grading and prognosis, and it carries mechanistic implications via linkage with PDGFRA, a feature also identified in the current study and interestingly identified in CGGA." (PMID 37760597, 2023). "Collectively, these results suggest that clemastine induced lasting alterations in PDGFRA+ BTICs and suppressed the propagation of these tumor cells." (PMID 37760589, 2023). "Altogether, our data show that depletion of tumor-induced slow-cycling PDGFRα+ MSCs through ADAM12 restores antitumor immunity." (PMID 37798557, 2023). "Our results show that the frequency of inactivating CDKN2A/RB1 alterations is highest after tumor progression following post-operative combination therapy, and PDGFRA/MET alterations co-appear with CDKN2A inactivation." (PMID 37932833, 2023). "Only one tumor (1/9, 11%) demonstrated focal amplification of PDGFRA on chromosome 4q12, and only one tumor (1/9, 11%) demonstrated focal homozygous/biallelic deletion of CDKN2A and CDKN2B on chromosome 9p21." (PMID 38079020, 2023). "We also found PDGFRA CNA in the recurrent tumor as well as the xenograft model and upregulated protein expressions in the PI3K/AKT/mTOR pathway and RAS/RAF/MEK/ERK pathway in the recurrent tumor." (PMID 38012788, 2023). "We used PDGFRA+ BTIC cultures as the prototypic models with the rationale that the OPC-like status of these tumor cells can facilitate assessing their progenitor versus differentiated states." (PMID 37760589, 2023). "The increased presence of GALC+ and reduced presence of PDGFRA+ cells, together with the mutually exclusive staining pattern of these proteins, suggest these tumor cells indeed became more differentiated upon clemastine treatment." (PMID 37760589, 2023). "Fluoresce in situ hybridization analysis of platelet-derived growth factor receptor alpha revealed deletion in 42% of the tumor cells studied." (PMID 38098096, 2023). "We also found amplifications of CDK4 and MDM2 with PDGFRA gain in the recurrent tumor and upregulated protein expressions of these genes." (PMID 38012788, 2023). "In DFT2, focal copy number amplification of PDGFRA is shared by all DFT2 tumours and remains a strong early driver candidate." (PMID 37079675, 2023).
tumor (continued). "Sorafenib has tumor-agnostic efficacy in patients with tumors harboring genomic alterations in PDGFRA/B, VEGF-Rs, Flt-3, KIT, FGFR1 or the RAF/MEK/ERK pathway." (PMID 37444551, 2023). "Both tumor and fibroblast expression of PDGFRα and PDGFRβ was significantly correlated in pre-treatment and relapse samples and high post-treatment tumor and fibroblast PDGFRβ levels were associated with a short time to treatment failure (TTF)." (PMID 36909339, 2023). "In particular, it is well documented that PDGFRA signaling in malignant cells, and also tumor stroma and vasculature, is involved in the development and progression of several malignancies by promoting cell proliferation, migration and angiogenesis." (PMID 37673888, 2023). "Anti-tumor efficacy assessed by Choi criteria in the PDGFRA D842V population showed that 25/28 patients achieved PR and the ORR was 89% (95% CI: 72%–98%)." (PMID 36477870, 2023). "Based on the putative copy‐number alterations in TCGA pan‐cancer datasets, the amplification or deletion of PDGFRA was determined in 10,967 samples in 32 types of tumor." (PMID 36043552, 2023). "Further, we confirmed lower levels of Fap mRNA in tumours from Snail1ME-KO when compared to Snail1ME-WT mice and in tdTomato+PDGFRα+ isolated fibroblasts from those tumours." (PMID 37516803, 2023). "The results also showed that PDGFRA expression was negatively correlated with tumor purity (Rho = −0.178, p = 1.97e − 02)." (PMID 35378770, 2022). "Microarray studies revealed that platelet-derived growth factor receptor alpha polypeptide (Pdgfr-alpha) is highly expressed in tumor cells." (PMID 36520265, 2022). "KIT/PDGFRA WT GISTs are also among the tumor types that have been shown to harbor NTRK fusions with frequencies of 5–25%." (PMID 35681640, 2022). "The predominant lineage in 309 harbored PIK3CAH1047R mutation while that of case 310 had a sub-branch with a subclonal PDGFRA amplification present in all tumor regions." (PMID 35642016, 2022). "Previously, our group reported that silencing of the adaptor molecule SH3 Binding Protein 2 (SH3BP2) downregulated KIT and PDGFRA and microphthalmia-associated transcription factor (MITF) levels and reduced tumor growth." (PMID 36551682, 2022). "For FAP and PDGFRα, weak staining was observed in the fibromuscular stroma compared to the positively stained regions in the tumor epithelium." (PMID 35530322, 2022). "Re-biopsy after disease progression showed that the tumor cells carrying rearranged NTRK2 were eliminated and the tumor cells with amplification of PDGFRA survived." (PMID 35135556, 2022). "TNS2 has been shown to dephosphorylate the insulin receptor substrate 1 (IRS-1) and decrease its activation, which in turn can lead to increased interaction between PI3K and PDGFRA, and thus, increased tumor growth." (PMID 35804982, 2022). "It is generally accepted that whereas oncogenic KIT and PDGFRA mutations are necessary for the neoplastic transformation of GIST, additional somatic genomic alterations are required for tumor progression." (PMID 35284037, 2022). "Our results showed that known tumor mutations, including both KIT and PDGFRA, were detectable in ctDNA only among patients with metastatic GIST with measurable disease progression." (PMID 35273917, 2022). "A PDGFRα blocking antibody (Olaratumab) was tested for tumor treatment in phase 2 and 3 clinical trials." (PMID 35629326, 2022). "Tumor adaptation to KIT/PDGFRA inhibition leads to apoptosis evasion, and this antiapoptotic response is sustained over time by FGFR- and c-MET–mediated MAPK pathway reactivation." (PMID 36119525, 2022). "The PDGF-CC ligand was detected towards the end of the 1990s, and it has been proven to be related to tumor growth via paracrine signaling by means of PDGFRa." (PMID 35887839, 2022). "The expression of PD-L1 is heterogeneous in PDGFRA-mutant GISTs, and it is inversely related to tumor size, suggesting the inhibition of tumor proliferation and a better prognosis." (PMID 36612211, 2022).